DNMT1 (DNA methyltransferase 1)
Diseases named in the same sentence as DNMT1 in open-access papers (continued):
Sharing a sentence is not in itself a finding about the gene and the disease.
lung carcinoma (continued). "miR-148a and miR-152 directly target DNMT1, restoring gene demethylation and inhibiting the EMT process in lung cancer cells." (PMID 41394878, 2025). "To analyze the gene expression of different DNMTs, we noticed an increasing trend in DNMT‐1, DNMT‐3A, and DNMT‐3B gene expression in hypoxic lung cancer cells compared to normoxia." (PMID 35658112, 2024). "Curcumin induces anti-lung-cancer effects by upregulating exosomal transcription factor 21 (TCF21) expression and downregulating DNA (cytosine-5)-methyltransferase 1 (DNMT1), i.e., a TCF21 suppressor." (PMID 38892270, 2024). "gDEC is a next-generation DNMT1-targeting drug that has been evaluated in multiple clinical trials in acute myeloid leukemia (AML), lung cancer, and ovarian cancer." (PMID 37345101, 2023). "In lung cancer, CCL2 expression was attenuated by EZH2-mediated H3K27me3 in the enhancer regions and DNMT1-mediated DNA methylation in the promoter regions, impeding M2-like phenotype of macrophages thereby facilitating metastasis and infiltration." (PMID 37273004, 2023). "Given that DNMT3A/B can serve as an oncogene and a tumor suppressor gene in the lung cancer, the new inhibitors with selectivity toward DNMT1 and DNMT3A/B should be particularly highlighted in the new drug design of DNMT inhibitors (DNMTi)." (PMID 37628829, 2023). "IL-6 regulates the JAK2/STAT3 axis to up-regulate DNA methyltransferase 1(DNMT1), enhancing stem cell proliferation in lung cancer." (PMID 36550571, 2022). "The depletion of DNMT1 and/or DNMT3B resulted in growth arrest, apoptosis, and reactivation of TSGs in lung cancer cell lines." (PMID 35205708, 2022). "Smoking has been shown to modulate DNA methyltransferase 1 (DNMT1) and histone modification enzymes that are involved in pathogenesis of lung cancer and COPD." (PMID 35330676, 2021). "For instance, TGFβ1 has been shown to induce decrease expression of DNA-methyltransferase 1 (DNMT1) and PD-L1 promoter demethylation, leading to PD-L1 overexpression in lung cancer cells that were undergoing EMT." (PMID 34381456, 2021). "In this study, we obtained eight lung cancer-related genes (CDC25C, TWIST1, HIF1A, DNMT1, PARP1, CDKN1A, CCNB1, and BIRC5) as seed nodes, using an RWR algorithm analysis to prioritize lung cancer related genes." (PMID 33193600, 2020). "For instance, the phytochemical PEITC reduces the expression of DNMT1, DNMT3A and DNMT3B, resulting in the induction of RASSF1A dependent apoptosis in lung cancer cells." (PMID 31963420, 2020). "In in vivo model of lung cancer, EGCG epigenetic action in down-regulating DNMT1 is accompanied by phospho-histone H2AX (γ-H2AX) and p-AKT reduction." (PMID 30563268, 2018).
lung carcinoma (continued). "The fungus dramatically increased GA up to 44.8 fold in the post-fermentation oolong tea extract (PFOTE), resulting in enhanced demethylation effects and a significant reduction in the nuclear abundances of DNMT1, DNMT3A, and DNMT3B in lung cancer cell lines." (PMID 29416619, 2018). "Next, we collected 50 human lung cancer specimens to study the correlation among USP24, p300, β-TrCP and DNMT1 in human lung cancer." (PMID 30266897, 2018). "Thus, inhibition of DNMT1 could be a promising therapeutic potential for lung cancer." (PMID 28840963, 2018). "More importantly, our in vivo data were consistent with the findings from that in vitro, confirming the enhanced effect of BBR in the presence of MET on inhibition of lung cancer 8, 60, 61, and regulation of SP1, PDPK1 and DNMT1 expressions." (PMID 28840963, 2018). "In lung cancer samples, we also observed a significant overexpression of HDAC1, HDAC2, HDAC6 and also DNMT1 and DNMT3A." (PMID 28634396, 2017). "Finally, DBCCR1 may inhibit DNMT1 induction in lung cancers." (PMID 28427182, 2017). "We here also confirmed that the expression of DNMT1 is up-regulated in tumor tissues from NSCLC, and lung cancer cell lines." (PMID 28938637, 2017). "Our results demonstrated that the DNMT1 and c‐Jun acted as the potential downstream effectors of EP4 in mediating the anti‐lung cancer responses of solamargine." (PMID 27620163, 2017). "Along with the examination of TC1, expression levels of DNMT1, β-catenin, TCF4, Axin, Dab2, and Chibby were also examined in 84 lung cancer specimens." (PMID 28968956, 2017). "Mechanistically, our results indicated that the activation of phosphorylation of SAPK/JNK signaling, regulation and interaction between p65, DNMT1, and EZH2 protein/gene were involved in the anti-lung cancer effect of PPI in this process." (PMID 27421653, 2016). "Protein levels of DNMT1, DNMT3b, and HDAC in the HPV16-positive or HPV16 E6-transfected lung cancer cells were higher than in the HPV-negative or HPV16 E6 knockdown cells." (PMID 26918347, 2016). "More importantly, our in vivo data were consistent with the findings from that in vitro, confirming the effect of PPI on lung cancer growth inhibition and regulation of SAPK/JNK, p65, DNMT1 and EZH2 protein expression levels." (PMID 27421653, 2016). "In other terms, our data suggest that the global DNA hypomethylation induced by the disruption of DNMT1/PCNA interactions acts such as an oncogenic event of the brain, breast, mesothelial and lung cancers." (PMID 24637615, 2014). "A recent study combining cell, animal and clinical lung cancer tissues as a modelfound that, NNK attenuates DNMT1 degradation and also induces its nuclear accumulation resulting in subsequent hypermethylation of promoters of tumour suppressor genes." (PMID 23596512, 2013). "For example, DNMT1 and DNMT 3b overexpression in lung cancer cells has been correlated with promotor hypermethylation and silencing of the tumor suppressor gene p16 in lung cancer cells." (PMID 24130964, 2013). "Moreover, stable “knock-down” of DNMT1 prior to carcinogen exposure was sufficient to prevent cellular transformation, and it is well established that aberrant DNA CpG methylation is a well frequent event in lung cancer leading to the inactivation/dysregulation of critical genes." (PMID 24212667, 2011). "MG98 and siRNA directing to DNMT1 mRNA induced lower DNMT1 level and reexpression of RASSF1A, CDKN2A in culture lung cancer CALU-6, and A549 cells have been demonstrated." (PMID 20119531, 2009). "In vitro and in vivo studies have revealed the oncogenic role of NAA10 in lung cancer, demonstrating that NAA10 binds to DNMT1 and positively regulates its enzymatic activity by facilitating DNMT1′s binding to DNA and its recruitment to the promoters of tumor suppressor genes, such as E-cadherin." (PMID 40558489, 2025).
lung carcinoma (continued). "Thus, the knockdown of DNMT1 by using the CRISPR/Cas9 system would be a new strategy to repress proliferation, migration, and invasion of lung cancer cells." (PMID 36091786, 2022). "Additionally, miRNA-29b, down-regulates indirectly and directly DNMT1 and DNMT3A/3B expression respectively in AML patients and along with miRNA-29a cooperatively target DNMT3A/3B expression in lung cancer, while they are both down-regulated in AML." (PMID 36555712, 2022). "The mRNA and protein levels of DNMT1 were increased in E2-treated A549 and PC14 lung cancer cells." (PMID 35589688, 2022). "Epigenetic mechanisms could be involved in CCL2 repression in neuroblastoma, as recently described in lung cancer, where epigenetic silencing of CCL2 by DNMT1 and the EZH2/H3K27me3 axis potentiates tumor development by inhibiting macrophage infiltration." (PMID 36923280, 2022). "USP24 promotes cancer malignancy by inducing IL-6 by stabilizing p300 and beta-transducing repeats-containing proteins (β-TrCP) to boost histone-3 acetylation and NF-B while lowering DNA (cytosine-5)-methyltransferase 1 (DNMT1) in M2 macrophages and lung cancer cells." (PMID 35884607, 2022). "In lung cancer cells undergoing epithelial–mesenchymal transition (EMT), tumor growth factor-beta 1 (TGF-β1) decreases expression of the DNA methyl-transferase 1 (DNMT1), an enzyme that methylates the CD274 promoter, thus resulting in increased PD-L1 expression." (PMID 33114576, 2020). "It has been reported that this compound upregulates p16, p21, and p27gene expression by inhibition of DNMT1 activity in bladder transitional carcinoma cells T24, pancreatic carcinoma CFPAC-1 cells, colon carcinoma HCT15, SW48, and HT-29, and lung carcinoma CALU-1 cell lines." (PMID 33841535, 2020). "Nevertheless, there is a lack of information in lung cancers regarding the mechanism of DNMT1 upregulation." (PMID 28427182, 2017). "Lung cancer tissues (n=20) showed enhanced expression of DNMT1 than corresponding non-neoplastic tissues." (PMID 28938637, 2017). "Increased formation of phospho-H2AX observed in human lung carcinoma cells exposed to ionizing radiation and decreased levels of phospho-H2AX with increased expression of DNMT1 by histone deacetylase (HDAC) inhibitors further support our results in malignantly transformed renal epithelial cells." (PMID 27655674, 2017). "Since DNMT1 has previously been shown to regulate MEG3 expression through methylation in human hepatocellular carcinoma and hepatic stellate cells, we next wanted to determine the effect of DNMT1 knockdown on MEG3 levels within these lung cancer cell models." (PMID 27832204, 2016). "In this study, we demonstrated the inhibitory effect of PPI on lung cancer cell growth through stress-activated protein kinase/c-Jun N-terminal kinase (SAPK/JNK)-mediated inhibition of NF-kB subunit p65 and DNMT1 protein levels, subsequently; this resulted in the reduction of EZH2 gene expression." (PMID 27421653, 2016). "Furthermore, our study suggested that DNMT1 was upstream of EZH2 and that interplay of DNMT1 and EZH2 were responsible for the overall responses of PPI in the inhibition of lung cancer cell growth." (PMID 27421653, 2016). "Lastly, it is also possible that DNMT1 affects gene expression by mechanisms independent of DNA methylation, as it has been demonstrated earlier in lung carcinoma." (PMID 26258530, 2015). "As an example, USP24, a deubiquitinating enzyme upregulated in M2 macrophages of lung cancer cells, could stabilize HAT p300 thus increase H3 acetylation and NF-κB while decrease DNMT1, subsequently elevating TNF-α and IL-6 transcription, ultimately resulting in cancer malignancy." (PMID 37273004, 2023).
lung carcinoma (continued). "The reduction of DNMT1 led to a decrease in the incidence of lung cancer induced by tobacco carcinogens, and DNMT activity was also reduced in pneumocytes that could give rise to lung cancer." (PMID 32751889, 2020). "An experimental study has demonstrated that this agent incorporates into DNA and exhibits cell growth inhibition by DNMT1 inhibition in human cancer cell lines, including T24 bladder cancer, SW48, HCT15, and HT-29 colon cancer, PC3 prostate cancer, CFPAC-1 pancreatic cancer, and CALU-1 lung cancer." (PMID 33841535, 2020). "A negative correlation between USP24 and DNMT1 was observed in human lung cancer specimens." (PMID 30266897, 2018). "Results in vitro showed that knockdown of DNMT1 by siRNA, similar to the 5-Aza-CR, could re-express RASSF1A and APC by demethylating their promoter regions, and could promote apoptosis, inhibit proliferation and migration of two lung cancer cell lines." (PMID 28938637, 2017). "Moreover, we demonstrated that knockdown of DNMT1 in vivo could also enhance the RASSF1A and APC expression via demethylation, and delayed the lung cancer growth with reduced adverse side effects." (PMID 28938637, 2017). "While in the presence of miR-101, the expression of DNMT1 and DNMT3B did not change significantly, indicating that DNMT3A is a direct target of the miR-101 in lung cancer cells." (PMID 32751889, 2020). "In another study, when the level of DNMT1, DNMT3A and -3B in lung cancer cell lines were normalized against PCNA, no over-expression of DNMTs were observed, suggesting overexpression of some of these genes may be a reflection of increased cell proliferation." (PMID 20119531, 2009). "Interestingly, our results demonstrated a central role of DNMT1 expression that mediated the effect of β-elemene on NSCLC cell growth suggesting the potential target of β-elemene and involvement of DNMT1 in lung cancer cell viability, which were never been reported before." (PMID 25598321, 2015).
colon carcinoma (156 papers, 2008 to 2025). "DNMT1 has already been reported to interact with lncRNAs, e.g., in colon cancer, and the deregulation of DNMT1-associated lncRNAs was proposed to contribute to aberrant DNA methylation and gene expression in colon tumorigenesis." (PMID 37880732, 2023). "For example, important elevations of DNMT3B and DNMT1 expression have been associated with tumorigenesis, particularly in colon cancer (CC)." (PMID 37107631, 2023). "For example, hematological diseases like acute myeloid leukemia (AML) have mutations in the DNMT3A gene, whereas inactivating mutations in DNMT1 are related to genome-wide alterations of DNA methylation in colon cancer." (PMID 36012258, 2022). "A DNMT1-associated lncRNA, the DACOR1-lncRNA (DNMT1-associated Colon Cancer Repressed 1), is down-regulated in colon tumors." (PMID 36555712, 2022). "One of them, DACOR1 (DNMT1-associated colon cancer repressed lncRNA 1) is highly expressed in normal colon but is suppressed in various colon tumors and patient-derived cancer cell lines." (PMID 33142861, 2020). "A previous study showed that treatment of 5-AZA-2′-deoxycytidine (5-AZA-CdR) causes a decreased DNMT1 expression and increased p21 expression in colon cancer SW480 cells." (PMID 32731382, 2020). "LncRNAs can regulate genome-wide DNA methylation in association with the methyltransferase DNMT1, especially DACOR1 (DNMT1-associated Colon Cancer Repressed lncRNA 1), which has a highly tissue-specific expression in the normal colon." (PMID 31430887, 2019). "One of the best-studied systems in humans consists of HCT116 colon cancer cells carrying a hypomorphic allele in the DNMT1 gene together with a DNMT3B knockout (HCT116 DKO cells)." (PMID 29598829, 2018). "We recently demonstrated that a subset of long non-coding RNAs (lncRNAs) associates with the major DNA methyltransferase DNMT1 in human colon cancer cells, and the dysregulation of such lncRNAs contribute to aberrant DNA methylation patterns." (PMID 30348202, 2018). "As a control HCT116 colon cancer cells which are WT or have a homozygous mutation in DNMT1 (KO) are shown: the DNMT1-specific top band is indicated by the arrowhead at right." (PMID 29598829, 2018). "DNMT1 mutations in colon tumors and DNMT3A mutations in hematological malignancies have been observed in the cancer genome." (PMID 28127428, 2017). "Among them, the authors identified one lncRNA, referred to as DACOR1 (DNMT1-associated Colon Cancer Repressed lncRNA 1), that is highly and specifically expressed in normal colon tissue while repressed in colon cancer cell lines." (PMID 27408682, 2016). "Since both DNMT1 and DNMT3a are unable to compensate for DNMT3b loss, it is plausible that colon carcinoma cells contain an unidentified component of the DNA methylation pathway which is absent in PC3 cells." (PMID 18798999, 2008). "Taken together, we have identified genes of unknown function in radiosensitivity that are hypomethylated in response to radiation and show corresponding alterations in DNMT1 association and gene expression in colon cancer cells." (PMID 25887185, 2015). "Moreover, loss of DNMT1 in human colon cancer cell lines contributes to growth impairment." (PMID 31507632, 2019). "A year later, an increase in the expression and activity of DNMT1 enzyme was reported using RT-PCR and DNA-MTase Activity Assays in human colon cancer." (PMID 41226543, 2025). "It has been reported that GPR109a expression is decreased in colon cancers and several colorectal cancer cells, regulated directly or indirectly via methylation through DNMT1." (PMID 40864733, 2025). "Inactivation of DNMT1/3b in colon carcinoma cells induced a partial epithelial-mesenchymal transition associated with increased CD44 variant exon skipping." (PMID 38784389, 2024). "Treatment with the DNMT1 inhibitor 5-Azacytidine attenuated gene silencing in different colon cancer cell lines." (PMID 38302503, 2024).